SNORD115-24 (small nucleolar RNA, C/D box 115-24)
Synonyms: HBII-52-24
Gene: Small nucleolar RNA gene on chromosome 15 (25,213,648 to 25,213,729, forward strand). Ensembl gene ENSG00000200398.
Gene Ontology:
Biological process: RNA processing
Cellular component: nucleolus
Homologues: Orthologues: macaque SNORD115 (91% identical). Paralogues in human: SNORD115-26 (93% identical), SNORD115-6 (93% identical), SNORD115-11 (91% identical), SNORD115-29 (91% identical), SNORD115-34 (91% identical), SNORD115-36 (91% identical), SNORD115-41 (91% identical), SNORD115-42 (91% identical), SNORD115-43 (91% identical), SNORD115-12 (90% identical), SNORD115-15 (90% identical), SNORD115-16 (90% identical), and 37 more.